RUNX3 (RUNX family transcription factor 3)
Diseases named in the same sentence as RUNX3 in open-access papers (continued):
Sharing a sentence is not in itself a finding about the gene and the disease.
melanoma (continued). "In this study, by using cellular models of mouse melanoma, we uncovered a specific Runx3-regulated transcriptional profile that contained DEGs that encoded some ECM proteins, as well as DEGs that were inversely associated with increases in the metastatic potential." (PMID 33672337, 2021). "Runt-related transcription factor-3 (Runx3) is a tumor suppressor, and its contribution to melanoma progression remains unclear." (PMID 33672337, 2021). "miR-532-5p expression is upregulated in melanoma cells and metastatic melanoma tumors, and anti-miR-532-5p oligomers upregulate RUNX3 expression, suggesting that several different miRNAs targeting RUNX3 have specific functions in different types of cancer." (PMID 26375442, 2015). "Interestingly, the expression level of the tumor suppressor gene RUNX3 was found to be inversely correlated with that of miR-532-5p from the miR-532-502 cluster in primary melanomas." (PMID 25888956, 2015). "Accumulating reports suggest that Runx3 is critical for various melanomas." (PMID 23846726, 2013). "The 12 CpG loci identified by PAM analysis that provided the most accurate prediction of melanoma were RUNX3_P393_R, RUNX3_P247_F, RUNX3_E27_R, COL1A2_E299_F, MPO_P883_R, TNFSF8_E258_R, CD2_P68_F, EVI2A_P94_R, OSM_P188_F, ITK_P114_F, FRZB_P406_F, and ITK_E166_R." (PMID 21375697, 2011). "Whether Runx3 is a metastasis suppressor in melanoma is an important issue." (PMID 33672337, 2021). "As Runx3 suppressed metastasis of B16-F10 cells and B16-F0 cells are known to have a lower metastatic potential than B16-F10 cells, we believe that the level of Mal gene expression is correlated with the metastatic potential among the melanoma cells used in this study." (PMID 33672337, 2021). "Similarly, the tumour suppressor RUNX3 has been shown to be downregulated in metastatic melanoma lines when compared to primary melanoma or healthy skin, while expression of the chemokine and leucocyte chemoattractant CCL5 in B16 cells strongly suppresses lung metastasis." (PMID 29193607, 2018). "The EZH2-mediated elevation of H3K27me3 has been described to be involved in epigenetic silencing of the tumor suppressor genes RUNX3 and CDH1 in advanced-stage human melanoma tissues." (PMID 35163453, 2022). "One exception is melanoma, where levels of both H3K27me3 and EZH2 were found increased, and silenced transcription of the tumor suppressor genes E-cadherin and RUNX3." (PMID 36371348, 2022). "Here, we studied the two critical Runx transcription factors, Runx2 and Runx3, in regulating the transcription of TSP-1 in osteoblasts and melanoma cells, respectively." (PMID 23846726, 2013). "Moreover, as a transcription factor, RUNX3 is important in the development and maturation of immune cells, including T cells and thus could be involved in the alterations in immune gene promoter methylation observed between melanomas and nevi." (PMID 21375697, 2011). "First, it was reported that Runx3 expression is frequently lost in melanoma and that there is a good negative correlation between Runx3 expression and melanoma malignancy." (PMID 33672337, 2021). "Our study suggests that self-entrapping of metastatic Runx3-negative melanoma cells via adhesion and the actin cytoskeleton could be a powerful therapeutic strategy." (PMID 33672337, 2021). "These experiments demonstrate that DNA methylation of the non-CG island P2 promoter of IGF1 can directly silence gene expression, as previously shown when plasmid constructs containing the non-CG island promoters of LAMB3 and RUNX3 genes were transfected into HaCaT cells and 623 melanoma cells." (PMID 25789079, 2015). "RUNX3 was previously reported to be hypermethylated in 23% of melanoma cell lines but only infrequently in 4% of primary melanomas, but nevi were not examined in this study, making it unclear whether RUNX3 methylation levels were relatively increased or decreased with the acquisition of malignancy." (PMID 21375697, 2011).
glioma (26 papers, 2013 to 2025). A benign or malignant brain and spinal cord tumor that arises from glial cells (astrocytes, oligodendrocytes, ependymal cells). "Therefore, we explored the potential pathway involving miR-19/RUNX3/β-catenin trying to elucidate the related mechanism in glioma, also suggesting that miR-19 may be a possible diagnostic therapeutic approach that deserves further evaluation in GBM." (PMID 29340016, 2017). "Glioma patient studies indicate that RUNX3 is progressively inactivated through promoter hypermethylation, with reduced protein expression associated with disease progression." (PMID 40430278, 2025). "Another study showed that miR-19a/b inhibition in vitro and in vivo GBM models resulted in repression of glioma cell proliferation partially by upregulating RUNX3, followed by blocking of the Wnt/β-catenin pathway." (PMID 32906592, 2020). "Glioma patients who survived longer than 2-years more likely have highly RUNX3 expressed tumours than shorter surviving patients." (PMID 31467531, 2019). "Reexpression of RUNX3 in U87-MG cells significantly reduced glioma cell viability compared to control transfection." (PMID 31467531, 2019). "RUNX3 methylated gliomas were more likely to be high grade than low grade and gene methylation was associated with older patient age." (PMID 31467531, 2019). "MSP analysis revealed positive RUNX3 promoter methylation (below in the text: RUNX3 methylation) in 44 (32.4%) out 136 of glioma patient tumour specimens." (PMID 31467531, 2019). "The methylation status and protein expression levels of RUNX3 were measured by methylation-specific PCR and Western blot in 136 and 72 different malignancy grade glioma tissues, respectively." (PMID 31467531, 2019). "RUNX3 protein expression reduction was observed in the majority of studied glioblastoma specimens as compared to lower-grade gliomas." (PMID 31467531, 2019). "Although RUNX2 and RUNX3 were also the malignant predictors of glioma, they have a poor specificity for distinguishing Mes types." (PMID 31754093, 2019). "The results demonstrate that RUNX3 gene methylation and protein expression downregulation are glioma malignancy dependent and contribute to tumour progression." (PMID 31467531, 2019). "Majchrzak-Celińska and colleagues showed RUNX3 promoter methylation changes in different grade gliomas where methylation frequency was consistently increasing along with glioma grade, 0%; 22%; 52%; 62.5%, grades I; II; III; IV, respectively." (PMID 31467531, 2019). "Mueller with colleagues were first to show that RUNX3 is hypermethylated in glioblastoma cell lines and primary glioma tumour tissue cells compared to normal human brain tissue." (PMID 31467531, 2019). "In summary, miR‐19 promotes glioma cell migration mainly through the negative regulation on RUNX3, RhoB and LRIG1." (PMID 30073755, 2018). "Our data demonstrated that miR-19 and RUNX3 are considered as oncogene factor and tumor suppressor in glioma respectively, however, the functional roles of them as well as the underlying relationship between them remain poorly understood." (PMID 29340016, 2017). "Next, to analyze the mechanism of cell growth arrest caused by miR-19a/b inhibition, we assessed cell cycle distribution of glioma cells transfected with miR-19a/b inhibitor or control oligo as well as co-transfection between AS-miR19a/b and RUNX3 siRNA." (PMID 29340016, 2017). "In order to explore the function of RUNX3 on glioma malignant phenotype by AS-miR-19a/b in LN229 and U87 cell lines, we used the small interfering RNAs to knockdown the RUNX3 level." (PMID 29340016, 2017). "To verify the expression of RUNX3 besides tissue microarray, we used Real-time PCR and Immunohistochemical staining to detect clinical 43 resected glioma tissue samples." (PMID 29340016, 2017). "AS-miR-19a/b repressed the proliferation, invasion of glioma cells and targeted regulation for RUNX3 in vitro, we further examined its effect on tumor growth in vivo." (PMID 29340016, 2017).
glioma (continued). "Twenty pairs of human glioma tissues and their adjacent non‐cancerous tissues were analysed for RUNX3 expression by qRT‐PCR." (PMID 26756701, 2016). "The results showed that RUNX3 expression was generally inhibited in glioma tissues compared with the matched normal tissues." (PMID 26756701, 2016). "Our results also showed that RUNX3 was repressed in glioma tissue, and was inversely correlation with the malignancy of glioma." (PMID 26756701, 2016). "RUNX3 was shown to be down‐expressed in primary glioblastomas, and overexpression of RUNX3 in glioma cells resulted in significantly inhibited cell invasion and migration abilities." (PMID 26756701, 2016). "Our data showed that miR‐4295 targeted and subsequently repressed the expression of RUNX3, and overexpression of N‐myc promoted the level of miR‐4295 in glioma." (PMID 26756701, 2016). "Inhibition of N‐myc up‐regulated RUNX3 expression in glioma cells, however overexpression of miR‐4295 reversed the effect of N‐myc on RUNX3 expression." (PMID 26756701, 2016). "Here, we focused the roles of N‐myc, miR‐4295 and RUNX3 and searched the potential signalling pathway involving miR‐4295/RUNX3 trying to elucidate the involved mechanism in gliomas." (PMID 26756701, 2016). "Furthermore, SCARB2 and related genes significantly regulated glioma RUNX3/Notch and BMP signaling pathways Overall, our findings reveal SCARB2 as a key receptor for the oncolytic virus EV-A71, suggesting its promise as a therapeutic target in glioma." (PMID 41210942, 2025). "RUNX3 up-regulation in curcumin-treated cells likely contributed to reduced viability, migration, and increased apoptosis, aligning with its known tumor-suppressive function in gliomas." (PMID 40430278, 2025). "In glioma, miR-19a negatively regulates the expression of tumor suppressor proteins RhoB and RUNX3." (PMID 32906592, 2020). "Next, we analysed RUNX3 protein expression effect on glioma patient survival." (PMID 31467531, 2019). "Moreover, they suggested that RUNX3 expression is regulated by promoter methylation since increased mRNA levels of RUNX3 following 5-aza-dC treatment were found in glioma U87 cells." (PMID 31467531, 2019). "RUNX3 expression evaluation at protein level was performed on the same glioma samples applying Western blot (WB) analysis, and in a total 72 glioma specimens, among which 6 were astrocytoma grade I, 27 grade II, 17 grade III, and 22 grade IV (glioblastoma) were used." (PMID 31467531, 2019). "However, there was no report indicated the potentially regulatory and signaling pathway involving miR-19/RUNX3 in glioma." (PMID 29340016, 2017). "In conclusion, our study validates a pathogenetic role of miR-19 in glioma and establishes a potentially regulatory and signaling involving miR-19 /RUNX3/β-catenin, also suggesting miR-19 may be a candidate therapeutic target in glioma." (PMID 29340016, 2017). "Moreover, our data also indicated that RUNX3 is frequently downregulated in gliomas cell lines and tissue specimens with qRT-PCR, western blot and immunohistochemical staining respectively (data not shown)." (PMID 29340016, 2017). "Furthermore, our data demonstrated that RUNX3 is a direct target of miR-19 and suppression of miR-19 inhibited glioma cell proliferation, invasion and induced apoptosis at least partly through RUNX3, subsequently blocked the Wnt/β-catenin signaling pathway." (PMID 29340016, 2017). "To test whether miR-19a/b regulates RUNX3 expression in vitro, we used AS-miR-19a/b (miR-19a/b antisense oligonucleotide) to reduce the miR19a/b expression level in gliomas LN229 and U87 cell lines." (PMID 29340016, 2017). "Moreover, miR‐4295 mediates the expression of RUNX3 and effect proliferation, periodic blocking, and apoptosis of glioma cell." (PMID 26756701, 2016). "However, there was no direct evidence indicated the potentially regulatory and signalling pathway involving miR‐4295/RUNX3 in gliomas." (PMID 26756701, 2016).
glioma (continued). "Our aim was to investigate the genetic background of N‐myc/miR‐4295/RUNX3 and to identify a new marker that might play a role in gliomas behaviour." (PMID 26756701, 2016). "Moreover, inhibition of miR‐4295 was sufficient to restore RUNX3 expression repressed by N‐myc in glioma cells." (PMID 26756701, 2016). "In brief, these results may validate a pathogenetic role of a miR‐4295 in gliomas and establish a potentially regulatory and signalling pathway involving N‐myc/miR‐4295/RUNX3 in gliomas." (PMID 26756701, 2016). "Further, a study has found that the PIWIL1/piRNA-DQ593109 (piR-DQ593109) complex is a major regulator of blood-tumor barrier (BTB) permeability in glioma through the MEG3/miR-330-5p/RUNX3 axis, and their inhibitions could enhance efficient delivery of anti-glioma drugs to glioma tissues." (PMID 36009578, 2022). "In the present study for the first time RUNX3 promoter methylation and protein expression was analysed in the same specimens of brain tumour to reveal if the link of RUNX3 methylation and silencing which was shown in glioma cell lines meet the similar processes in astrocytoma specimens." (PMID 31467531, 2019). "Moreover, RUNX3 methylation was considered as a potential biomarker of aggressiveness of gliomas." (PMID 31467531, 2019). "Furthermore, accumulating evidence demonstrated RUNX3 could inhibit the proliferation, tumourigenic and metastasis of glioma cells." (PMID 26756701, 2016). "Thus, we can get a conclusion that N‐myc mediated‐miR‐4295 inhibited RUNX3 expression in glioma." (PMID 26756701, 2016). "However, N‐myc protein also could bind to the promoter of pri‐miR‐4295, and inhibit the expression of RUNX3 in the glioma cells." (PMID 26756701, 2016). "In addition, N‐myc protein also could bind to the promoter of pri‐miR‐4295 and inhibit the expression of RUNX3 in glioma cells." (PMID 26756701, 2016). "We observed that SCARB2 and positively correlated genes influenced the RUNX3/Notch signaling and BMP pathway in glioma." (PMID 41210942, 2025). "Previously, we and others found that Wnt/β-catenin signaling is hyperactivated in glioma cells due to promoter methylation of its antagonists, including SFRP1 and RUNX3." (PMID 34681943, 2021). "Previously, we found that RUNX3 methylation correlates with WHO tumor grade and glioma patients’ age." (PMID 32783304, 2020). "Forty‐six glioma samples and one non‐neoplastic brain sample were analyzed by MS‐HRM in terms of SFRP1, SFRP2, RUNX3, CBLN4, INA, MGMT, and RASSF1A promoter methylation." (PMID 32783304, 2020). "In our previous study, we found that RUNX3, being a downstream molecule of TGF-β, inhibited glioma cell invasion and migration by regulating the MMP-2 protein expression and enzyme activity." (PMID 23457532, 2013). "Interestingly, we observed a general decrease in promoter DNA methylation of RASSF1A with increasing glioma malignancy (this effect was also observed to a lesser extent for SFRP1, MGMT, and RUNX3)." (PMID 32783304, 2020). "Nevertheless, low sample numbers and the lack of information about RUNX3 alterations in lower-grade gliomas decided the appearance of wider RUNX3 analysis in sample number-rich glioma studies." (PMID 31467531, 2019). "In summary, our study provides new insights into the role of miR-19a/b in human glioma and confirms that miR-19 is able to inhibit RUNX3 expression level through directly binding to the 3′UTR region of RUNX3 which medicates the suppression of β-catenin/TCF4 transcription." (PMID 29340016, 2017). "Our previous study has shown that a panel of 12 genes including ERCC1, hMLH1, ATM, CDKN2B (p15INK4B), p14ARF, CDKN2A (p16INK4A), RASSF1A, RUNX3, GATA6, NDRG2, PTEN, and RARβ might be useful in evaluation of glioma aggressiveness." (PMID 25648363, 2015). "Meanwhile, we also demonstrated that RUNX3 was down-regulated in GBM cell lines and glioma tissues (data not shown)." (PMID 29340016, 2017).
leukemia (25 papers, 2009 to 2025). A malignant (clonal) hematologic disorder, involving hematopoietic stem cells and characterized by the presence of primitive or atypical myeloid or lymphoid cells in the bone marrow and the blood. "In contrast to RUNX1 and RUNX3, whose mutations are closely linked to the promotion of leukemia and GC, respectively, the initial studies suggest that RUNX2 acts as a master regulator of osteoblast differentiation and bone development." (PMID 33313404, 2020). "Consistently, histological analysis showed that AML mice in Runx3 KD group had fewer leukemia cell infiltration in the peripheral blood, spleen, and liver." (PMID 34722267, 2021). "We observed that Runx3 knockdown significantly inhibited leukemia progression by inducing DNA damage to enhance apoptosis in murine AML cells." (PMID 34722267, 2021). "Altogether, these results illustrate that Runx3 knockdown induces DNA damage and apoptosis in leukemia cells in vivo." (PMID 34722267, 2021). "For RUNX3, the methylation-mediated expression regulation has been observed to play a role in leukemia and solid tumors." (PMID 34294773, 2021). "The number of RUNX3 peaks and corresponding genes in the leukemia group was significantly higher than those in the normal cells." (PMID 34722267, 2021). "Reduction of Runx3 in leukemic cells therefore appeared to induce G0/G1 arrest, which was consistent with a reduction of leukemia burden." (PMID 34722267, 2021). "RUNX3 peaks were enriched at introns, promoters, intergenic sites, and exons of genes in normal cells and leukemia cells." (PMID 34722267, 2021). "An elevated Runx3 expression is significantly correlated with poor overall survival in patients with leukemia, which seems consistent with the role of Runx3 as an oncogene." (PMID 32751884, 2020). "Runx3 is expressed in human cells of hematopoietic origin and increased in most cell lines of leukemia." (PMID 32751884, 2020). "An interesting study recently highlighted that runt-related transcription factor 3 (RUNX3) is involved in MSC-mediated protection of leukemia cells from As2O3- (arsenic trioxide-) induced apoptosis." (PMID 28947904, 2017). "The search for the association between age of leukemia onset, leukocytosis, and the blasts content in the bone marrow with the relative RUNX3 expression did not provide statistically significant results (p = 0.954, p = 0.910, p = 0.810, respectively)." (PMID 36005134, 2022). "Since all these data suggest that RUNX family members are crucial for normal hematopoiesis and change in their structure or expression can cause leukemia development, the aim of this study was to evaluate RUNX1 and RUNX3 relative expression level in adult acute lymphoblastic leukemia cases." (PMID 36005134, 2022). "Besides, dysfunction of RUNX3 resulted in defects of transcriptional regulation and DNA repair, leading to bone marrow failure, which may progress to leukemia." (PMID 40650112, 2025). "AI-10-49 is of particular interest for treatment of (inv16) AML as it inhibits RUNX1 binding to CSF1R, RUNX3 and CEBPa promoter targets and also strongly increases mice survival in CBFβ-MYH11 murine leukemia cell models by reducing leukemia burden." (PMID 29921764, 2018). "To evaluate the effects of Runx3 reduction, we first sorted green fluorescent protein (GFP)+ leukemia cells from Vector and Runx3 KD AML mice and confirmed that shRNA specific for Runx3 led to decreased RUNX3 expression by qRT-PCR and Western blot analysis (80.3% reduction of Runx3 mRNA expression)." (PMID 34722267, 2021). "For instance, 26% of non-CBF AML patients overexpressed RUNX3 in comparison with HSC whilst 13% had lower levels, similar to that observed in CBF leukemia." (PMID 35490198, 2022).